NOTCH1 (notch receptor 1)
Diseases named in the same sentence as NOTCH1 in open-access papers (continued):
Sharing a sentence is not in itself a finding about the gene and the disease.
breast cancer (continued). "Notch1 signaling is activated at a significantly higher rate in TNBC compared to other subtypes of breast cancer." (PMID 35186194, 2022). "In breast cancer cell lines, doxorubicin induced Notch-1 signaling which led to increased ABCC1 expression." (PMID 35163586, 2022). "Meaningfully, paeoniflorin has been found to exert a tumor suppressor effect in breast cancer, including inhibiting the proliferation and metastasis of breast cancer cells by inhibiting the Notch-1 pathway." (PMID 35154350, 2022). "Using optoNotch we confirm that NOTCH1 activation increases cell proliferation in MCF7 and MDA-MB-468 breast cancer cells in 2D and spheroid 3D cultures, although causing distinct cell-type specific migratory phenotypes." (PMID 35585598, 2022). "The modulation of glucose-6-phosphate dehydrogenase (G6PD)/ HIF-1α expression by Nrf2 is consequently involved in the Notch1 pathway-mediated regulation proliferation, migration, and invasion of breast cancer." (PMID 36289931, 2022). "CAFs have been reported to facilitate the maintenance of breast cancer cell stemness via the CCL2/NOTCH1 pathway, and perostin, which is an important component of the ECM derived from fibroblasts, is essential for sustaining breast cancer stemness." (PMID 36244987, 2022). "For example, Kim and coworkers demonstrated that HO-1-derived CO production participated in the manifestation of breast cancer stem cell-like properties and stimulated the formation of mammospheres through activation of Notch-1 signaling." (PMID 36230727, 2022). "Though Notch1 is the most common activated oncogene in tumors, the coexpression of Notch1 and Notch4 is frequently observed in breast cancer." (PMID 36226253, 2022). "In breast cancer, the functioning of NOTCH genes is diverse, corresponding to the molecular subtype of tumor, i.e., NOTCH1 can induce HER2 transcription and cause an increase in the mammary stem cells and breast CSCs." (PMID 36429127, 2022). "Increased Notch signaling followed by the accumulation of the intracellular domain of Notch1 was detected in a wide variety of human breast carcinomas." (PMID 36017236, 2022). "Mechanistically, direct contact of macrophages with breast cancer cells induces Notch1-dependent MenaINV expression in breast cancer cells." (PMID 33783686, 2021). "Another study reported that Notch1 mediated repression of PTEN in HER2+ breast cancer cells and was responsible for trastuzumab resistance through increased survival of breast cancer cells." (PMID 33968932, 2021). "Different rearrangements in Notch1 and Notch2 were found in a subset of breast cancer patients and cell lines, mostly triple negative breast cancers." (PMID 34572582, 2021). "An example of this interplay is explained in cervical and breast cancers where Notch1 forms a complex with the kinase IKK, which represents the core element of the NF-κB cascade, thus allowing its nuclear translocation." (PMID 35582386, 2021). "In our previous study, we showed that PIM kinases phosphorylate Notch1 to promote tumorigenicity of estrogen receptor (ER)–positive breast cancer cells." (PMID 33775697, 2021). "To test the idea that Notch and Wnt function antagonistically to dictate mammary tumor histology, we sought to reduce Notch1 signaling in the context of PI3K-induced mammary tumor formation." (PMID 34475389, 2021). "High Notch-1 protein expression was suggested as a marker to predict poorer survival in women with HER2+ breast cancer." (PMID 34322664, 2021). "In clinical trials, patients with HER2-positive breast cancers with high JAG1 or NOTCH1 expression show low overall survival." (PMID 34374886, 2021). "Notch receptors (Notch1–4) play critical roles in tumorigenesis and metastasis of malignant tumors, including breast cancer." (PMID 34006834, 2021). "Rencently, KRT19 was found to interact with β-catenin/RAC1 complex and regulated NUMB and Notch1 expression, leading to the enhancement of the cancer stem-like cell properties in breast cancer." (PMID 33442422, 2021).
breast cancer (continued). "The consequence of circRNA-000911 down-regulation in breast cancer is the up-regulation of miR-449a and down-regulation of Notch1." (PMID 33976116, 2021). "In each of these studies, the miRNA was able to reduce breast cancer stemness markers or sensitize breast cancer cells to chemotherapy, and this was accomplished in part due to the direct targeting of Notch1." (PMID 33916548, 2021). "Clinical studies have revealed an association between high-level expression of NOTCH1 and JAG1 in breast cancer and poor prognosis." (PMID 34374886, 2021). "Paeoniflorin suppressed cell proliferation by inhibiting Notch-1 signaling pathway in breast cancer cells." (PMID 33531900, 2021). "In another example, Notch1 was necessary to induce trastuzumab resistance in breast cancer in vitro and in vivo." (PMID 34322664, 2021). "One more flavonoid luteolin decreased growth and invasion of breast cancer cells through Notch1 inhibition." (PMID 34680255, 2021). "For example, ALDH activity was regulated by another putative CSC marker Nanog, through the Notch1/Akt signaling pathway in breast cancer stem cells." (PMID 34322664, 2021). "Notch1/3/4 signalling is anti-apoptotic in the breast, and hence promotes breast cancer cell survival." (PMID 34295896, 2021). "Paeoniflorin, the active ingredient in Paeoniae Radix Alba, inhibits the proliferation and invasion of breast cancer cells by inhibiting the Notch-1 signaling pathway." (PMID 34857023, 2021). "In triple negative breast cancer, BRD4 can also promote breast cancer migration and invasion by regulating Jagged1 and Notch1 signaling expression." (PMID 34834420, 2021). "Within breast cancer, the role of Notch2 has been controversial, with some studies finding that it has a tumour suppressive role, in direct contrast to the Notch1 and 4 isoforms." (PMID 34295896, 2021). "In pancreatic cancer cells, XN reduced Notch1 expression and activity and induced apoptosis; in breast cancer, it showed anti-proliferative, anti-metastatic, and pro-apoptotic effects and enhanced anticancer Th1 immune response." (PMID 34680255, 2021). "Using breast cancer cell lines, we found that mutant forms of NOTCH1 or NOTCH2 collaborate with EZH2 to mediate the transcriptional repression of PTEN in these poor-prognosis breast cancers." (PMID 33750924, 2021). "Overexpression of Notch1 overlaps with ALDH1 expression in breast cancer tissues and significantly correlates with high grade, metastasis, and TNBC." (PMID 34889737, 2021). "A study reported that paeoniflorin suppressed the invasion of breast cancer cells by targeting Notch-1 pathway." (PMID 33531900, 2021). "For example, in general, basal-like breast carcinoma has been known to harbor mutations involving BRCA1, CCNE1, AKT3, or MYC; however, these genes were largely wild type, and NOTCH1 mutations were relatively common in our SeC-EOs." (PMID 34638295, 2021). "Upregulation of Notch1 of endothelia is correlated with poor prognosis in human cancer tissues, such as melanoma, serous ovarian carcinoma, lung adenocarcinoma, breast carcinoma, and colorectal carcinoma." (PMID 33672457, 2021). "HER2 can reduce binding between Notch1 ligands and their receptors and, in consequence, decrease the activated level of Notch1 and influence breast cancer cells’ proliferation." (PMID 34068438, 2021). "Increased levels of EZH2 and SIP enhance NOTCH1 activation and signaling leads to increased tumorigenic ability in mice and breast cancer patient- derived mammospheres." (PMID 32033146, 2020). "Analysis of the human breast cancer database revealed a close correlation between high expression levels of NOTCH1 and TNBC incidence, especially BRCA1-related TNBC." (PMID 32591500, 2020).
breast cancer (continued). "The majority of the research reported to date focuses on Notch 1 signalling as oncogenic pathways in breast cancer." (PMID 32575680, 2020). "Activated Notch1 repressed p27 to promote cell cycle and proliferation in cancers such as prostate cancer, adenoid cystic carcinoma, and breast cancer." (PMID 32630477, 2020). "On the other hand, Notch1 hyperactivation has been linked to the etiology of T-cell acute lymphoblastic leukemia (T-ALL) and chronic lymphocytic leukemia (CLL), breast cancer, adenoid cystic carcinoma and mantle cell lymphoma." (PMID 32796631, 2020). "In the future, we will further explore the mechanism of other targets of lncRNA SNHG3, and explore the role of Notch 1 and Notch 3 in breast cancer." (PMID 32883233, 2020). "Similar to breast cancer and T‐cell acute lymphoblastic leukemia, the regulation of the Notch1 pathway by targeting BRD4 suggests an epigenetic mechanism." (PMID 33135348, 2020). "In human breast cancer, increased expression of Jagged-1 and Notch-1 are significantly correlated with poor prognosis." (PMID 32549768, 2020). "In order to further explore the regulatory mechanism of ID4 on MRP1, we used TCGA to analyze the main downstream signaling pathways of ID4 in breast cancer and found that Notch1 pathway has been involved in many development processes." (PMID 32328189, 2020). "Overexpression of Notch1 and/or Jagged1 predicts the poorest overall survival outcome for women with breast cancer." (PMID 33003540, 2020). "To further strengthen the pathological correlation between Notch1-Zeb1 signaling and stemness properties in human breast cancer, we performed immunohistochemical staining for Zeb1, NICD and ALDH1 in 175 cases of primary breast carcinoma." (PMID 33046710, 2020). "In breast cancer, endothelial Jagged1 was found to activate Notch1 in neighboring breast cancer stem cells, upregulating Zeb1, which in turn increases Vegfa production and further activates the tumor neovasculature." (PMID 33198378, 2020). "TIMP knockout induces CAF-like phenotype in fibroblasts; exosomes derived from TIMPless fibroblasts are rich in ADAM10; exosome delivered ADAM10 promotes cell motility and activates Notch1 and RhoA signaling in breast cancer cells." (PMID 32957712, 2020). "NOTCH1 protein levels are increased in DYRK2 knockout human breast cancer cell lines, leading to a rise of the invasion and migration potential of these cells compared to the wild type." (PMID 32462403, 2020). "There are reports that confirms overexpression of Delta 1 and Jagged 1 in breast cancer, while Notch-1 also plays an important role in the origination of human mammary tumor in the form of a downstream effector of oncogenic Ras." (PMID 32245065, 2020). "CCL2 induced Notch1 expression and the cancer stem cell features in breast cancer cells, constituting a “cancer–stroma–cancer” signaling circuit." (PMID 33244467, 2020). "Gamma-secretase cleaved activated Notch1 and Notch3 proteins have been detected in majority of breast cancer cell lines." (PMID 32211044, 2020). "On one hand, a lot of literature confirmed the promoting role of Notch1 in pancreatic cancer, breast cancer, prostate cancer and ovarian cancer." (PMID 32547317, 2020). "Breast cancer cells expressed Notch1 and Notch4 proteins at variable steady-state levels regardless of the ER status." (PMID 32636747, 2020). "In this study, we demonstrated that ID4 regulates the drug resistance of breast cancer by connecting with Notch1 in a new way." (PMID 32328189, 2020). "To further investigate the potential function of ID4 in chemo-resistance, we analyze the TCGA database and found that the expression of ID4 correlated with the Notch1 pathway in breast cancer." (PMID 32328189, 2020). "Reduction of MSI1 expression in breast cancer cell lines decreased the NOTCH1, c-MYC, ERBB2, and ERK1/2 expressions, which eventually inhibited the survival of tumor cells." (PMID 32448364, 2020).
breast cancer (continued). "In vitro studies using ER+ breast cancer lines provided the initial evidence that Notch activation contributes to resistance to endocrine therapy and that targeting Notch1 or Notch4 by using genetic or pharmacologic means reversed this resistance." (PMID 33003540, 2020). "Both populations were highly tumorigenic – as few as 50 to 100 CD44+/CD24− and CD133+ breast cancer cells induced tumors in NOD/SCID mice – and expressed stem cell associated genes, including Oct4, Notch1, Aldh1, Fgfr1 and Sox1." (PMID 32430004, 2020). "Here the authors show that tumor endothelial Jagged1 induces activation of Notch1 signaling and increases Zeb1 expression in neighboring breast cancer stem cells, promoting tumor aggressiveness." (PMID 33046710, 2020). "In breast cancer cells, Notch1 or Notch4 can promote the expression of Slug by activating the Slug promoter." (PMID 32636747, 2020). "So Notch1-MCAM signaling pathway is possibly another method leading to endocrine resistance in breast cancer." (PMID 32636747, 2020). "The Notch pathway is implicated in targeted treatment resistance in ErbB2/HER2 positive breast cancer, which is potentially attributed to the coregulation between Notch 1 and ErbB2/HER2 signalling." (PMID 32575680, 2020). "For example, overexpression of Notch1 and Jagged1 predict the poorest overall outcome for women with breast cancer, with a predicted mortality of 63% in women with JAG1high-expressing tumors, compared to 32% in JAG1low-expressing tumors." (PMID 33003540, 2020). "The inhibition of Notch1 has been shown to reverse the Jagged1-induced EMT process in human breast cancer cells." (PMID 32630477, 2020). "A positive correlation between the expression of ID4 and C-promoter binding factor-1(CBF1, a critical downstream transcriptional factor in Notch1 signal pathway) was observed in both TNBC breast cancer cell lines." (PMID 32328189, 2020). "In breast cancer models, Notch1 was induced by fibroblast-derived CCL2 to maintain a stem cell phenotype and had a possible oncogenic role." (PMID 32028262, 2020). "Further, we found that this upregulation of NOTCH1 was required for tumor initiating cell induction in multiple breast cancer cell lines." (PMID 32391382, 2020). "Hoey and colleagues used monoclonal antibody against DLL4 ligand to block its binding to Notch1, thus observing antitumor effects in a wide range of human tumor xenografts from various tumor types, including breast cancer." (PMID 31379945, 2019). "The cytotoxic effect of CDDP was higher for MDA-MB-231 cells with altered Notch1 activity than native breast cancer cells." (PMID 31357442, 2019). "While in this study the expression of this protein was significantly down-regulated, previous study have shown that the upregulation of S100A16 expression promotes epithelial mesenchymal transition via the Notch1 pathway in breast cancer." (PMID 31877708, 2019). "Further study on Nrf2/G6PD/HIF‐1α/Notch1 signalling axis is demanded for realization of basal type breast cancer treatment." (PMID 30809937, 2019). "Next, to determine the mechanism by which Nanog can regulate the radiation response and ALDH activity in breast cancer cells, we assessed the expression and phosphorylation level of Akt and Notch1 in ALDH-positive and ALDH-negative cells." (PMID 30845764, 2019). "Stable breast cancer (BC) cell lines with increased and decreased activity of Notch1 were generated using a transfection method." (PMID 31357442, 2019). "Notch-1 is required for trastuzumab resistance by repressing PTEN expression to contribute to activation of ERK1/2 signaling in breast cancer cells." (PMID 31469661, 2019). "There was persistence of one dominant clone and emergence of four new subclones, one of which contained alterations in the known breast cancer driver NOTCH1." (PMID 30763338, 2019).
breast cancer (continued). "Overexpression of Notch can induce the migration of breast cancer cells while using siRNA to knock down the expression of Notch1 can reduce migration and invasion of breast cancer cells." (PMID 31057403, 2019). "It has been reported that E2 induced the recruitment of N1ICD to the Hes-1 promoter in breast cancer cells, and that Notch1 regulated expression levels of ERα in ER-positive breast cancer." (PMID 31122254, 2019). "It was also reported that HDAC8 was required to maintain Notch1 protein stability by protecting against degradation mediated by Fbxw7 in a deacetylase activity-independent manner in breast cancer." (PMID 31362948, 2019). "For example, paeoniflorin suppressed invasion of breast cancer cells through affecting Notch-1 signaling pathway." (PMID 30886866, 2019). "Modulation of glucose‐6‐phosphate dehydrogenase (G6PD)/ Hypoxia inducing factor 1α (HIF‐1α) expression by Nrf2 is therefore involved in the Notch1 pathway‐mediated regulation proliferation, migration, invasion of breast cancer." (PMID 30809937, 2019). "As2O3 has also been shown to be a Notch-1 inhibitor, inactivating the Notch Signalling pathway in breast cancer." (PMID 30646589, 2019). "EZH2 has been reported to bind to the NOTCH1 promoter in TN breast cancer, and to bind to ERα protein." (PMID 31122254, 2019). "C-Myc is an important direct target of Notch1 in various cancers, such as T-cell lymphoblastic leukemias, breast cancer, lung adenomas and head and neck squamous cell carcinoma." (PMID 31395064, 2019). "In summary, our findings suggest that Nrf2 contributes to metastatic ability of basal type breast cancer cells through G6PD/HIF‐1α/Notch1 signalling axis." (PMID 30809937, 2019). "We supposed that Nrf2 regulate cells migration in breast cancer by controlling Notch1 and changing EMT." (PMID 30809937, 2019). "In breast cancer tissue, aberrant high levels of NOTCH1 and NOTCH2 were found in comparison with control tissue." (PMID 31443481, 2019). "Using the TCGA breast cancer dataset, we found that the expression of NOTCH1 was significantly higher in basal tumors than in all other subtypes of disease (Figure 4A1)." (PMID 31105691, 2019). "This study led to the findings that inhibiting Notch-1 in luminal breast cancers maintains the ER positive state for the effective targeting of ER-based therapies." (PMID 29298879, 2018). "Taken together, these studies suggest a mutual functional repression between Notch1 and ERα signaling in breast cancer EMT, where ERα-responsive genes (e.g., MTA3) would repress the expression of EMT-transcription factors laying downstream the Notch pathway." (PMID 29996493, 2018). "A recent study demonstrated that BRD4 was the upstream regulator of Jagged1 expression and Notch1 signaling, and played an important role in sustaining breast cancer migration and invasion." (PMID 30029633, 2018). "Previous study shows that via AP-1-dependent upregulation Notch-1 inhibition restores TRAIL-mediated apoptosis in MDA-MB-231 breast cancer cells, and LAD cells." (PMID 29581832, 2018). "Both Notch1 and Notch4 are found to have differential activities in breast cancer cell lines and patient samples, with Notch4 being the major receptor in the CSC populations of luminal and basal breast cancer cell lines." (PMID 30061899, 2018). "Subsequently, we showed that in luminal breast cancer cells, Notch1, and IKKα are recruited to ERα-responsive elements and activate ER-dependent transcription in an estrogen-independent fashion." (PMID 30564555, 2018). "We confirmed that 8 genes—MAPK14, CLOCK, NF2, HMGA2, CXCL12, E2F1, NOTCH1, and CD24—are associated with breast cancer." (PMID 30013305, 2018). "In cervical cancer as well as ER+ breast cancer cells, respectively, Notch1 activates NF-κB and ERα-dependent transcription and triggers recruitment of IKKα to the chromatin." (PMID 30564555, 2018).